RB1 (RB transcriptional corepressor 1)
Diseases named in the same sentence as RB1 in open-access papers (continued):
Sharing a sentence is not in itself a finding about the gene and the disease.
retinoblastoma (continued). "During the present work, we studied the phenotype of three different point mutants on the Rb1 gene observed in retinoblastoma patients: pD718N, pN328H, and pR552* with an HA-Tag." (PMID 39845333, 2025). "RB1 was the first cloned TSG, and its germline mutations with high penetrance account for half of retinoblastoma cases." (PMID 40904703, 2025). "This study evaluated 136 participants with retinoblastoma and demonstrated that MSK-ACCESS, a cfDNA and buffy coat DNA-matched clinical assay, can detect mosaic RB1 variants with VAFs as low as 1%." (PMID 40338593, 2025). "Retinoblastoma, which involves only a single tumor suppressor Rb1, clearly taught us that there were two important periods for mutation and the two mutation mechanisms were necessary in reproducing both the unilateral and bilateral cases." (PMID 40569505, 2025). "It successfully predicted the existence of the tumor suppressor gene known as "Rb1" by effectively demonstrating the overall patterns observed in clinical data covering both bilateral and unilateral retinoblastoma cases." (PMID 40569505, 2025). "Some evidence for liquid biopsy identification of RB1 in other cancers exists, primarily focusing on retinoblastoma (aqueous humor cfDNA), but emerging evidence also exists for bladder urothelial carcinoma (urinary cfDNA and exosomes)." (PMID 40805181, 2025). "In retinoblastoma, hypermethylation of RB1 occurs in about 9% of unilateral sporadic tumors and can affect any of its 27 cytosine–phosphate–guanine (CpG) sites." (PMID 41150792, 2025). "RB1 has been quite the subject, after discovery, of characterization and cloning efforts that enriched our understanding of TSGs and mechanisms of retinoblastoma tumorigenesis and also revealed patterns of inheritance in susceptibility to cancer." (PMID 40227591, 2025). "Only in our cell models did differences become apparent after MYCN knockdown, when RB1−/− cell lines showed more pronounced expression of the photoreceptor signature than RB1-proficient retinoblastomas." (PMID 39079981, 2024). "Taken together, this paper contributes to the understanding of regulatory events in RB1-proficient MYCN-overexpressing retinoblastoma." (PMID 37606819, 2024). "The MYCNA amplified RB1-proficient retinoblastoma tumours also have distinct molecular signatures from RB1-deficient tumours." (PMID 37606819, 2024). "DNA methylation and gene expression profiling in further RB1-proficient MYCN-amplified retinoblastomas will help to better characterize differences in molecular circuitry in RB1−/− and RB1-proficient MYCN-amplified retinoblastoma." (PMID 39079981, 2024). "It has been said that RB1 methylation above the LOH and mutations are required for complete molecular diagnoses of retinoblastoma." (PMID 39132504, 2024). "Our findings therefore provide guidance on the optimal AH collection time point and genetic testing strategy for the successful analysis of somatic RB1 variation in retinoblastoma patients undergoing conservative treatment." (PMID 38672657, 2024). "For instance, the GWAS studies on retinoblastoma show that it is caused by MDM2 and CDKN1A mutations in addition to RB1 mutation." (PMID 38540335, 2024). "The identification of somatic RB1 variation is crucial to confirm the heritability of retinoblastoma." (PMID 38672657, 2024). "Here we aimed to define the impact of MYCN activity in the context of retinoblastoma subtypes 1 and 2 in a cohort of 61 retinoblastoma samples enriched by six RB1-proficient MYCNA and two extraocular metastatic relapse samples." (PMID 39079981, 2024). "Retinoblastoma is a childhood cancer of the developing retina that starts with biallelic inactivation of the retinoblastoma gene 1 (RB1) gene." (PMID 38473926, 2024).
retinoblastoma (continued). "RB1-proficient MYCNA retinoblastomas are currently considered a separate disease entity with very aggressive behavior, in which MYCN is thought to exclusively drive tumorigenesis." (PMID 39079981, 2024). "This subtype 2-MYCN (cluster C) comprises not only the rare RB1-proficient MYCNA retinoblastoma but also RB1−/− retinoblastomas with overactive components of MYCN signaling." (PMID 39079981, 2024). "While this is a relatively large group of the exceedingly rare RB1-proficient retinoblastomas, the comparison is limited by small cohort size, such that batch effects cannot completely be excluded." (PMID 39079981, 2024). "The RB1 gene, responsible for retinoblastoma development, was first cloned and identified in the year 1986." (PMID 38540335, 2024). "Recognizing that SKP2 loss causes synthetic lethality in RB1 null cells, Aubry and colleagues explored the therapeutic potential of the SKP2 inhibitor MLN4924 in treating retinoblastoma." (PMID 38672640, 2024). "RB1-proficient retinoblastoma has been described as a separate retinoblastoma entity with very aggressive behavior, in which MYCN is thought to be the exclusive driver of tumorigenesis." (PMID 39079981, 2024). "Weri-Rb1 and Y79 are the only retinoblastoma cell lines analyzed in the depmap database, and both express low levels of CDA mRNA." (PMID 38332874, 2024). "Nearly all retinoblastomas develop following biallelic inactivation of RB1 gene, located in humans on chromosome 13—more specifically, 13q14.1-q14.2." (PMID 39000021, 2024). "Retinoblastoma usually begins in the developing retina with the inactivation of the RB1 tumor suppressor gene, followed by further genomic abnormalities." (PMID 38332874, 2024). "The majority of heritable retinoblastoma cases can be identified through screening of the RB1 gene using a peripheral blood sample." (PMID 38672657, 2024). "Variants in the RB1 gene are associated with retinoblastoma (RB) development, and their presence in germline cells considerably increases the risk of subsequent malignant neoplasms (SMNs) in RB survivors." (PMID 39596402, 2024). "Retinoblastoma emerges due to detrimental alterations in the RB1 gene, specifically located on the long arm of chromosome 13 at the 13q14 locus." (PMID 38792122, 2024). "The sequences of B4GALNT1 and GAPDH, both in chromosome 12, are highly conserved in retinoblastomas, and in genomic regions away from areas that include frequent alterations such as RB1 (chromosome 13q) and MYCN (chromosome 2p)." (PMID 36148636, 2023). "We previously reported the development of an LB assay for retinoblastoma using as little as 100 microliters of the aqueous humor of the eye and ultra-low-pass WGS to detect RB1 mutations and RB-associated CNAs25–27." (PMID 36805676, 2023). "Classical examples include the loss of hypoxanthine-guanine phosphoribosyl transferase (HPRT) to model Lesch-Nyhan syndrome and disruption of the tumor-suppressor RB transcriptional corepressor 1 (RB1) to model retinoblastoma." (PMID 37712424, 2023). "Despite being rare, retinoblastoma gained interest within the scientific community since RB1 gene is the first tumour suppressor gene to be discovered." (PMID 37667345, 2023). "For instance, a small but significant percentage of retinoblastoma cases are genetically marked by MYCN amplification in a wild-type RB1 background." (PMID 36982482, 2023). "TNBC constitutes 10% to 15% of all breast cancers, and an important component to distinguish the presence of TNBC is retinoblastoma (RB1) status." (PMID 38137912, 2023). "Cell free RB1 alteration results of unilateral retinoblastoma patients: Pre-enucleation and post-enucleation." (PMID 36735656, 2023). "Retinoblastoma results from the inactivation of both copies of RB1, a gene located on chromosome 13q14.2." (PMID 37932687, 2023). "Circulating tumor RB1 DNA (ctDNA) is found in the blood (plasma) of retinoblastoma patients at diagnosis before instituting treatment (naïve)." (PMID 36735656, 2023).
retinoblastoma (continued). "For this example, we present a 6‐month‐old child with retinoblastoma owing to a de novo mosaic deletion on 13q involving multiple genes, including RB1." (PMID 36910590, 2023). "Retinoblastoma is an aggressive rare childhood cancer of the developing retina that is initiated by biallelic RB1 gene inactivation." (PMID 37658463, 2023). "Hypermethylation resulting in epigenetic silencing was first demonstrated in the studies of retinoblastoma patients, in which hypermethylation was discovered in the promoter of the retinoblastoma tumor-suppressor (RB1) gene." (PMID 35721189, 2022). "Previously, we showed that RB1–/– retinoblastomas are heterogeneous and express different levels of genes related to vision (photoreceptorness score), which is positively correlated with the amount of differentiation observed at the histologic level." (PMID 36245757, 2022). "Retinoblastoma is the most common intraocular tumor in children and is initiated by the biallelic inactivation of the retinoblastoma 1 (RB1) gene." (PMID 35992823, 2022). "Our study demonstrates that retinal organoids derived from the RB1 mutant pluripotent stem-cell model certain aspects of retinoblastoma in vitro." (PMID 35565295, 2022). "Integrated analysis, based on gene expression, methylation, and methylation-expression correlations, was performed to identify distinct molecular components of MYCN-amplified RB1-proficient retinoblastomas compared with other retinoblastoma subtypes." (PMID 36245757, 2022). "In this study, we explored unique transcriptomic and epigenomic features of MYCN-amplified RB1-proficient retinoblastomas compared with other retinoblastomas." (PMID 36245757, 2022). "Transcriptome analysis of RB1 knockout organoids and primary retinoblastoma revealed gain of a retinoblastoma expression signature in the organoids, characterized by upregulation of RBL1 (p107), MDM2, DEK, SYK and HELLS." (PMID 35565295, 2022). "The methyltransferase MGMT (p < 0.05, FC = −4.8) and RB1 (p < 0.05, FC = −4.36) were significantly downregulated in Rb tumors." (PMID 35626705, 2022). "MYCN-amplified RB1-proficient retinoblastomas display significantly distinct molecular features compared with other retinoblastomas, including a set of 40 hypermethylation-driven downregulated genes." (PMID 36245757, 2022). "Cross-validation using the entire cohort and the public domain expression data verified the overall lower expression of these genes not only in retinoblastomas with a MYCN-amplified RB1-proficient background, but also in MYCN-amplified neuroblastomas." (PMID 36245757, 2022). "A large number of genes (n = 3155) were identified with distinct expression patterns in MYCN-amplified RB1-proficient retinoblastomas." (PMID 36245757, 2022). "In conclusion, although MYCN-amplified RB1-proficient tumors reside within the molecular spectra of retinoblastoma, they still possess significant differences in expression and methylation patterns that distinguish them from the other retinoblastoma tumors." (PMID 36245757, 2022). "In a retinoblastoma organoid model derived from genetically engineered hESCs with a biallelic mutagenesis of RB1, the tyrosine kinase SYK was significantly upregulated." (PMID 36077628, 2022). "Data integration identified a 40-gene expression signature with hypermethylated state resulting in a significant downregulation in MYCN-amplified RB1-proficient retinoblastomas." (PMID 36245757, 2022). "Studies from retinoblastoma, a cancer initiated by biallelic inactivation of the RB1 gene, defined a central role of RB in epigenetic control and a key role of RB/E2F-regulated chromatin remodelers in tumorigenesis." (PMID 36068209, 2022).
retinoblastoma (continued). "We showed that genes upregulated in MYCN-amplified RB1-proficient retinoblastomas were significantly enriched for translation and mRNA synthesis processes, whereas downregulated genes were enriched for cell cycle regulation pathways." (PMID 36245757, 2022). "Further, we measured real-time OCR rates in Rb null and RB1-complemented WERI-Rb1, Y79 and GL1-RB1 retinoblastoma cells." (PMID 36291051, 2022). "Retinoblastoma is an aggressive childhood cancer initiated by the bi-allelic inactivation of RB1 in developing retina." (PMID 36012581, 2022). "The transcriptomic profiling of RB1-complemented Y79 shows differentially regulated cell cycle and metabolic pathways that corroborated with findings in Rb tumors." (PMID 35626705, 2022). "In this study, we over-expressed MYCN in the developing chicken retina and in human embryonic stem cell (hESC)-derived retinal organoids to model MYCNA-driven retinoblastoma in RB1+/+ genetic background." (PMID 35729105, 2022). "This methylation was first described in retinoblastoma patients, and in vitro experiments confirmed that Rb1 contains a CpG island, which, when methylated, strongly reduces Rb1 expression." (PMID 35267571, 2022). "Overall, the results showed that MYCN-amplified RB1-proficient retinoblastomas do possess distinct molecular signatures that diverge them from MYCN-silent or RB1-null retinoblastoma, or both." (PMID 36245757, 2022). "Variants found in cases of the cancer cohort were in genes: RB1 and NF1, both coherent with the phenotype of the patients: Retinoblastoma and Neurofibromatosis type 1, respectively." (PMID 35087072, 2022). "Together our data provide robust evidence that RB1-null hESC and patient-specific homozygous RB1−/− organoids mimic the development and malignant transformation that occurs in vivo resulting in Rb tumors." (PMID 35325233, 2022). "The expression pattern of these genes clearly separates MYCN-amplified RB1-proficient tumors from other retinoblastomas, observed in both in-house and public-domain patient cohorts." (PMID 36245757, 2022). "A similar and increased expression of both photoreceptor and E2F cell cycle regulatory genes are seen in several RB1 mutant retinoblastoma cell lines with MYCNA." (PMID 35729105, 2022). "Retinoblastoma (RB) constitutes the most universal intraocular malignancy commonly resulting from the RB tumor suppressor gene (Rb1) inactivation, with the characteristic manifestations of vision decline, red and irritated eyes, and leukocoria." (PMID 35248107, 2022). "The present analysis reconfirmed the clustering of MYCN-amplified RB1-proficient wild-type tumors within a retinoblastoma subbranch characterized by lower photoreceptorness." (PMID 36245757, 2022). "Retinoblastoma (Rb) is a deadly childhood eye cancer that is classically initiated by inactivation of the RB1 tumor suppressor." (PMID 35984874, 2022). "Rescuing RB1 or HK1 in retinoblastoma cells shifted the cellular metabolic profile to glycolysis dependence, consequently reducing mitochondrial ATP production." (PMID 36291051, 2022). "Differential methylation profiling identified a large number of significantly hypomethylated and hypermethylated genes in MYCN-amplified RB1-proficient wild-type tumors compared with MYCN-silent retinoblastomas." (PMID 36245757, 2022). "Models to understand retinoblastoma development and the role of RB1 therein have been established in mice, human fetal retina tissue, cell lines and most recently as 3D retinal organoids." (PMID 35565295, 2022). "DNA sequencing of retinoblastoma tumors has demonstrated few, if any, additional genetic alterations beyond those in the RB1 gene." (PMID 35368709, 2022). "MYCN-amplified RB1-proficient (MYCNARB1+/+) retinoblastomas are diagnosed at an earlier age compared with classic RB1–/– retinoblastomas and display more aggressive clinical behavior." (PMID 36245757, 2022).
retinoblastoma (continued). "HK1 levels are significantly low in retinoblastoma tumors and RB1-null retinoblastoma cells, which is distinct from other types of solid tumors." (PMID 36291051, 2022). "YAP/TAZ plays a tumor suppressive role by inducing integrin alpha 5 and beta 5 in neural/neuroendocrine and RB transcriptional corepressor 1 (RB1)−/− solid cancers, such as retinoblastoma, small cell lung cancer, and neuroendocrine prostate cancer." (PMID 36294681, 2022). "Our results show that MYCN acts as an oncogene in RB1-proficient retinas, leading to neoplasia in two novel models of retinoblastoma: one with MYCN over-expression in the chicken retina and one in hESC-derived retinal organoids." (PMID 35729105, 2022). "Overall, it was shown that the hypermethylation observed in high MYCN-amplified RB1-proficient retinoblastomas has significant influence on global gene expression in this tumor subtype." (PMID 36245757, 2022). "To elucidate how RB1 influences HK1 and E2F2 expression in the context of cancer, we overexpressed the wild-type RB1 in Rb null WERI-Rb1 retinoblastoma cells in vitro." (PMID 35626705, 2022). "RB1 inactivation was present in most of the tumors of both retinoblastoma subtypes, but, nevertheless, a difference in stemness was observed between the two subtypes." (PMID 34552068, 2021). "In three retinoblastoma patients, chromothripsis disrupted the RB1 locus resulting in a gene fusion, and immunohistochemical (IHC) staining demonstrated complete absence of RB1 protein expression in the tumor." (PMID 33827698, 2021). "It has been postulated that biallelic inactivation of RB1 can result in benign retinomas and that subsequent genetic alterations are required for progression to retinoblastoma." (PMID 33670346, 2021). "We found that, compared to other cancers, RB1 in retinoblastoma is significantly and disproportionately more likely to display copy-neutral LOH rather than heterozygous loss LOH." (PMID 33466343, 2021). "The RB1 gene, located on chromosome 13, is a well-known tumor suppressor gene that was discovered in genetic studies of hereditary retinoblastoma." (PMID 33450701, 2021). "The vast majority of retinoblastomas initiate with biallelic inactivation of RB1 and a small subset (1–2%) initiate with MYCN amplification in the absence of RB1 inactivation." (PMID 34315877, 2021). "The eponymous member of the pocket protein gene family is RB1 or RB, which was named from an inherited eye tumor called retinoblastoma." (PMID 34136392, 2021). "The RB tumor suppressor gene (RB1) was originally isolated through positional cloning of a chromosomal segment frequently deleted in the childhood cancer retinoblastoma." (PMID 33668093, 2021). "Molecularly development of retinoblastoma is based on biallelic inactivation of the RB1 tumor suppressor gene." (PMID 34680218, 2021). "To identify further genotype-phenotype relationships, we developed the retinoblastoma variant effect classification (REC), which considers each variant’s predicted effects on the common causal mediator, RB1 protein pRB." (PMID 33807189, 2021). "While retinoblastomas are initiated by genetic alterations in RB1 or, rarely, MYCN, additional somatic changes have been identified that are thought to further drive tumourgenesis." (PMID 33805427, 2021). "To assess this, we compared the RNA and protein changes seen in RPE1 cells with the properties of RB1−/− human Retinoblastomas." (PMID 34404904, 2021). "Taken together, these data suggest that spontaneous retinoblastoma can form from patient-derived iPSCs differentiated into retinal organoids or be induced by CRISPR-Cas9 targeting of the RB1 locus in both hESCs and patient-derived iPSCs." (PMID 34315877, 2021). "Co-deletion of RB1, PTEN, and Rbl1 (p107) in mouse retinal progenitor cells caused fully penetrant bilateral retinoblastomas." (PMID 33591981, 2021).